SPPL2B (signal peptide peptidase like 2B)
Description:
Intramembrane-cleaving aspartic protease (I-CLiP) that cleaves type II membrane signal peptides in the hydrophobic plane of the membrane. Functions in ITM2B and TNF processing. Catalyzes the intramembrane cleavage of the anchored fragment of shed TNF (TNF), which promotes the release of the intracellular domain (ICD) for signaling to the nucleus. May play a role in the regulation of innate and adaptive immunity. Catalyzes the intramembrane cleavage of the simian foamy virus processed leader peptide gp18 of the envelope glycoprotein gp130 dependently of prior ectodomain shedding by furin or furin-like proprotein convertase (PC)-mediated cleavage proteolysis.
Synonyms: IMP-4; PSH4; IMP4; KIAA1532; PSL1
Tractability: Small molecule: a high-quality ligand is known. Antibody: UniProt places it where antibodies can reach, with high confidence; its Gene Ontology location is reachable by antibodies, with high confidence; UniProt predicts a signal peptide or a membrane-spanning region. PROTAC: ubiquitination databases record sites on it; its protein half-life has been measured; a small molecule that binds it is known.
Target class: Enzyme; Hydrolase
Gene: Protein-coding gene on chromosome 19 (2,328,613 to 2,355,095, forward strand). Ensembl gene ENSG00000005206.
Subcellular location: Cell membrane; Golgi apparatus membrane; Lysosome membrane; Endosome membrane; Membrane
Subcellular location (Human Protein Atlas): Nucleoplasm; Plasma membrane; Centrosome
Pathways (Reactome):
Signal Transduction: Regulation of TNFR1 signaling
Gene Ontology:
Molecular function: aspartic endopeptidase activity, intramembrane cleaving; protein binding; protein homodimerization activity
Biological process: membrane protein ectodomain proteolysis; membrane protein intracellular domain proteolysis; membrane protein proteolysis; regulation of immune response; regulation of tumor necrosis factor-mediated signaling pathway
Cellular component: cytoplasmic side of endoplasmic reticulum membrane; endosome membrane; Golgi-associated vesicle membrane; lumenal side of endoplasmic reticulum membrane; lysosomal membrane; membrane; plasma membrane; endosome; Golgi membrane
Genetic constraint (gnomAD): Loss-of-function variants: 40 observed, 46.98 expected, observed/expected ratio (o/e) 0.85, 90% interval 0.66 to 1.11. The synonymous counts are far from expectation, so gnomAD's model fits this gene poorly and the ratio says little. Missense variants: 865 observed, 763.88 expected, observed/expected ratio (o/e) 1.13, 90% interval 1.07 to 1.2. Synonymous variants: 419 observed, 331.54 expected, observed/expected ratio (o/e) 1.26, 90% interval 1.17 to 1.37.
Homologues: Orthologues: chimpanzee SPPL2B (92% identical), dog SPPL2B (81% identical), guinea pig SPPL2B (79% identical), pig SPPL2B (79% identical), mouse Sppl2b (77% identical), rat Sppl2b (76% identical), tropical clawed frog sppl2b (69% identical), zebrafish sppl2 (66% identical). Paralogues in human: SPPL2C (47% identical), SPPL2A (41% identical), SPPL3 (19% identical), HM13 (18% identical).
Diseases named in the same sentence as SPPL2B in open-access papers:
SPPL2B is named in the same sentence as 7 diseases in open-access papers, as found by Europe PMC text mining. Sharing a sentence is not in itself a finding about the gene and the disease. The quoted sentences say what the papers report.
Blindness (1 paper, 2018). Blindness is the condition of lacking visual perception defined as a profound reduction in visual perception. "In the CD4 cells of our patients, we found that SPPL2B expression was common to both those with raised WCC and jaw claudication whilst MATR3 was associated with raised WCC and long-term monocular blindness." (PMID 30037347, 2018).
breast carcinoma (1 paper, 2020). "With this hypothesis, the relationship between SPPL2b mRNA levels and the survival of patients with breast cancer was analyzed using The Cancer Genome Atlas data set." (PMID 32493324, 2020).
SPPL2B also shares sentences with these, for which no sentence is quoted: cancer (1 paper); diabetes (1); melanoma (1); Skin Tumor (1); tumor (1).